CD48 (CD48 molecule)
Diseases named in the same sentence as CD48 in open-access papers (continued):
Sharing a sentence is not in itself a finding about the gene and the disease.
glioblastoma (2 papers, 2022 to 2023). The most malignant astrocytic tumor (WHO grade IV). "In addition, the expression of CD48 has been shown to be upregulated throughout the development of glioblastoma, and patients with high CD48 expression have a poorer prognosis." (PMID 35480305, 2022). "The results revealed that glioblastomas of ArMRS high-risk group had significantly higher expression levels of CD44, CD48, CD276 (B7-H3), and PD1 (PDCD1) compared to low-risk group in the TCGA cohort, suggesting higher ArMRS may indicate more abundant expression of immunotherapy targets." (PMID 37214463, 2023).
graft versus host disease (2 papers, 2020 to 2021). An immune system disorder that occurs after allogeneic hematopoietic stem cell transplant and is a reaction of donor immune cells against host tissues. "The observation that CD48-hematopoietic antigen can synergistically triggers CD56dim NK cell cytotoxicity possibly provides a further rational for the lack of NK mediated graft versus host disease (GvHD) in KIR ligand-mismatched haploidentical hematopoietic transplantation." (PMID 32204481, 2020).
histiocytic sarcoma (2 papers, 2012 to 2020). An aggressive malignant neoplasm with a poor response to therapy, usually presenting as stage III/IV disease. "In this model, murine histiocytic sarcomas, equivalent to human myeloid sarcomas, emerged at the injection site 30–50 days after cell implantation and consisted of tightly packed monotypic cells that were CD48+, CD47+ and Mac1+, with low or absent expression of other hematopoietic lineage markers." (PMID 22952867, 2012).
multiple sclerosis (2 papers, 2015 to 2020). A progressive autoimmune disorder affecting the central nervous system resulting in demyelination. "Combined therapy of anti-CD48, anti-lymphocyte function-associated antigen 1 and fingolimod (a sphingosine 1-phosphate receptor modulator for multiple sclerosis treatment) keeps embryonic pig pancreas function in diabetic mice." (PMID 32046717, 2020).
myocardial infarction (2 papers, 2024 to 2025). Gross necrosis of the myocardium, as a result of interruption of the blood supply to the area, as in coronary thrombosis. "Although no studies have yet definitively established a direct link between CD48 and the pathogenesis of atherosclerosis (AS), myocardial infarction (MI), or heart failure (HF), CD48’s role in immune regulation suggests its potential involvement." (PMID 41019764, 2025).
Primary immunodeficiency (2 papers, 2019 to 2020). "Familial PAS+ E. coli + CD48/SLAM risk haplotype GC closely resembles very early onset, primary immunodeficiency related IBD and may serve to inform understanding of the etiopathogenesis and treatment of microbially driven intestinal inflammation across species." (PMID 32854367, 2020).
psoriasis (2 papers, 2022 to 2025). An autoimmune condition characterized by red, well-delineated plaques with silvery scales that are usually on the extensor surfaces and scalp. "As a result, immunostimulatory genes showed higher expression levels within psoriasis than normal tissues, such as CD86, CD48, TNFRSF4, TNFRSF25, ICOS, and CXCR4." (PMID 36685512, 2022).
sarcoma (2 papers, 2020). A usually aggressive malignant neoplasm of the soft tissue or bone. "Three hub genes (CD48, P2RY10, and RASAL3) associated with immunotherapy and the development of sarcomas were analyzed and presented, as potential prognostic biomarkers and/or therapeutic targets of immunotherapy for sarcomas." (PMID 33292275, 2020). "Freshly isolated primary sarcomas expressed activating ligands CD112 and low levels of CD155 and CD48 as well as the inhibitory ligands PCNA, MUC1, HLA-ABC, and HLA-DR/DP/DQ (n = 13)." (PMID 32082316, 2020). "In addition, immunohistochemistry (IHC) staining data acquired from the HPAD also confirmed the differential expression of the predicted genes (CD48, P2RY10, RASAL3) in sarcoma samples." (PMID 33292275, 2020).
acute GVHD (1 paper, 2022). "A predictive model using five of such polymorphisms (CXCL12 rs2839695, IL12A rs7615589, KIR3DL1 rs4554639, TGFB2 rs5781034 for the recipient and CD48 rs2295615 for the donor) together with the development of acute GVHD grade III/IV improved risk stratification of CMV reactivation." (PMID 35525883, 2022).
acute promyelocytic leukemia (1 paper, 2019). An aggressive form of acute myeloid leukemia (AML), characterized by arrest of leukocyte differentiation at the promyelocyte stage, due to a specific chromosomal translocation t(15;17) in myeloid cells. "In a separate study, expression of the oncogenic fusion proteins PML-RARA and AML1-ETO found in acute promyelocytic leukemia (APL) and some non-APL AMLs, respectively, was associated with the loss of the 2B4 ligand CD48 on the leukemia cell surface." (PMID 31681270, 2019).
adult T cell leukemia (1 paper, 2023). "Another study further confirmed the role of CD48 expression in evading NK-cell-mediated immunity in adult T cell leukemia/lymphoma (ATLL) cells." (PMID 37876793, 2023).
Alzheimer disease (1 paper, 2023). A progressive, neurodegenerative disease characterized by loss of function and death of nerve cells in several areas of the brain leading to loss of cognitive function such as memory and language. "With the elevation of CD48 and CD40 genes in Alzheimer's disease, associations of protein levels were also markedly increased in tissues." (PMID 36520044, 2023). "Indeed, the upregulation of both CD48 and CD40 genes was significantly increased in the severe Alzheimer's disease group." (PMID 36520044, 2023). "We observed a marked elevation of CD48 and CD40 genes in Alzheimer's disease." (PMID 36520044, 2023).
aortic stenosis (1 paper, 2025). Aortic valve stenosis is a aortic valve disease caused by the incomplete opening of the aortic valve. "In this study, we observed that CD48 exhibited stable expression patterns in both diseased tissues and peripheral blood samples, suggesting that CD48 may be involved in a common pathway linking aortic stenosis (AS) to heart failure (HF) progression." (PMID 41019764, 2025).
atherosclerosis (1 paper, 2025). A disease characterized by the build-up of fatty material and calcium deposition in the arterial wall resulting in partial or complete occlusion of the arterial lumen. "In conclusion, this study has identified a potential biomarker, CD48, using bioinformatics and machine learning algorithms, which provides a model for detecting atherosclerosis patients who have progressed to heart failure and also suggests potential therapeutic targets." (PMID 41019764, 2025). "In summary, we anticipate that CD48 may serve as a clinically relevant biomarker for predicting AS-to-HF progression, enabling earlier intervention and potentially improving long-term outcomes for patients with atherosclerosis." (PMID 41019764, 2025).
atrial fibrillation (1 paper, 2023). A disorder characterized by an electrocardiographic finding of a supraventricular arrhythmia characterized by the replacement of consistent P waves by rapid oscillations or fibrillatory waves that vary in size, shape and timing and are accompanied by an irregular ventricular response. "The dysregulation of Tfh (follicular helper T) cells induced by the interaction between CD48 and CD3D has been reported as a common pathogenic mechanism underlying the co-occurrence of dilated cardiomyopathy and atrial fibrillation." (PMID 37349706, 2023).
B-cell acute lymphoblastic leukemia (1 paper, 2025). A neoplasm of lymphoblasts committed to the B-cell lineage, typically composed of small to medium-sized blast cells. "Our study highlights the complex immune regulatory network involved in B-cell acute lymphoblastic leukemia (B-ALL), focusing on the interplay between VISTA, CD244, CD48, FOXD3, and PVRL2." (PMID 40610562, 2025).
breast tumours (1 paper, 2024). "Conversely, of the 511 CSRs overexpressed in breast tumours relative to healthy breast tissue, 72 were significantly underexpressed when compared to non-breast healthy tissues, including well-established drug targets like FGFR3, CD48, and CCR3." (PMID 38306344, 2024).
E. coli infection (1 paper, 2021). "To understand the overall changes of individual MK subpopulations under inflammatory conditions, we collected CD41+CD42d+ cells in the mouse BM for Smart‐Seq2 sequencing 36 h after E. coli infection when the proportion of CD48+ MKs peaked." (PMID 34042332, 2021).
fatty liver (1 paper, 2022). "Compared with normal controls, CD48 and NE positive cells were significantly higher in patients with mild and moderate fatty liver, and highest in patients with moderate NAFL." (PMID 36426356, 2022).
Hypertension (1 paper, 2022). The presence of chronic increased pressure in the systemic arterial system. "First, we generated hypertension with Ang-II, which increased the number of bone marrow Lineage– c-kit+ Sca-1+ CD150+ CD48− (SLAM–LSK), CMPs and GMPs." (PMID 35747128, 2022).
influenza (1 paper, 2016). An acute viral infection of the respiratory tract, occurring in isolated cases, in epidemics, or in pandemics; it is caused by serologically different strains of viruses (influenzaviruses) designated A, B, and C, has a 3-day incubation period, and usually lasts for 3 to 10 days. "721.221 cells (with and without influenza) were used as targets since they express an unknown tumor ligand for NKp46 and also cellular ligands for NTB-A (NTB-A) and 2B4 (CD48)." (PMID 26919106, 2016). "Because JEG-3 cells do not express CD48 (which is the 2B4 ligand) or NTB-A (which is the NTB-A ligand), prior to or following influenza infection, we hypothesized that both receptors might be involved in the killing of influenza and might recognize influenza virus proteins." (PMID 26919106, 2016).
invasive ductal carcinomas (1 paper, 2024). "An analysis of the expression of NF-kappa B (NF-κB) related genes using RT-PCR in inflammatory breast cancer revealed that CD48 was upregulated in these samples compared to invasive ductal carcinomas." (PMID 38476238, 2024).
ischemic heart disease (1 paper, 2021). "However, lots of DEGs were not previously reported in the investigation of VNS, such as CD163, CD48, DDit4, and ADAMTS1, which have been demonstrated close association with ischemic heart disease." (PMID 33981734, 2021).
liver cancer (1 paper, 2023). An epithelial or non-epithelial malignant neoplasm that arises from the liver. "Growth differentiation factor 15 (GDF15) facilitated tumor immunosuppression via interaction with CD48 on Treg cells and downregulation of E3 ligase STUB1, leading to accumulation of FOXP3 protein in liver cancer." (PMID 36733484, 2023).
lymphoid tumor (1 paper, 2023). "We initially wanted to identify CD48-positive lymphoid tumor cell lines." (PMID 37609636, 2023).
Nephroblastoma (1 paper, 2024). An embryonal neoplasm characterized by the presence of epithelial, mesenchymal, and blastema components. "Finally, the results showed that there were significant differences in CD80, CD48, IDO2, CD276, CD28, and CD200R1 between both groups, which could be used as potential therapeutic targets for the treatment of nephroblastoma." (PMID 38526609, 2024).
non-small cell lung carcinoma (1 paper, 2025). A group of at least three distinct histological types of lung cancer, including non-small cell squamous cell carcinoma, adenocarcinoma, and large cell carcinoma. "This also was observed with CD48 expressing non-small cell lung cancer, which was more susceptible to NK-killing." (PMID 40610562, 2025).
ovarian carcinoma (1 paper, 2022). A malignant neoplasm originating from the surface ovarian epithelium. "(c) statistically significant expression in ovarian cancer, closely related to the OS or DFS of ovarian cancer patients (favorable or unfavorable), but with both stimulatory and inhibitory potential on immune system (eg, CD48)." (PMID 35991556, 2022).
parasitemia (1 paper, 2025). "Interestingly, while percentages of proliferating cells for most MPPs peaked with parasitemia at day 11 p.i., CD48− HSCs had the highest proportion of EdU+ cells at day 15 p.i.." (PMID 40141458, 2025).
periodontitis (1 paper, 2025). An acute or chronic inflammatory process that affects the tissues that surround and support the teeth. "The intersection of these three machine learning approaches revealed six potential biomarkers associated with PANoptosis in periodontitis: PECAM1, CXCR4, SELP, IL2RG, CD48, and ZBP1." (PMID 40612110, 2025).
skin inflammation (1 paper, 2019). "Hh also reduced expression of other genes for inflammatory signaling pathways implicated in skin inflammation including TNFR (Tnfrsf25), JAK-STAT (Jak1), and NF-κB (Trl4, Myd88, Cd69, Cd48, Irf1)." (PMID 31264977, 2019).
systemic sclerosis (1 paper, 2018). A chronic disorder, possibly autoimmune, marked by excessive production of collagen which results in hardening and thickening of body tissues. "Recently, CD48 was shown to be associated with pulmonary inflammation in patients with systemic sclerosis." (PMID 30306094, 2018).
thymoma (1 paper, 2022). A neoplasm arising from the epithelial cells of the thymus. "Strikingly, in THCA and THYM (thymoma), NEIL3 was significantly associated with more than 20 immune checkpoint genes, such as CD86, ICOS, TNFSF4, and CD48, implying its role in regulating the tumor immune microenvironment." (PMID 36612106, 2022).
tumor (63 papers, 2008 to 2025). "Finally, tumor-associated macrophages expressed higher levels of CD48, mediating transient activation and subsequent dysfunction of NK cells via CD48-2B4 interactions." (PMID 32612950, 2020). "In addition, a bioinformatic analysis revealed that, compared to healthy kidneys, increased expression of CD85j, CD45, CD48 and PD-1 is a general characteristic of ccRCC and is strongly associated with an NK cell tumor infiltration signature in this type of tumor." (PMID 34149719, 2021). "It is suggested that neighboring T cells that express the CD48 receptor could help modulate an intermediary function, but also likely are two distinct mechanisms: the interaction of NK-cell 2B4 with tumor-associated CD48 and the 2B4–CD48 interactions among NK cells." (PMID 32630303, 2020). "Importantly, the exhaustion seen in NK cells co-cultured with tumor-associated CD48hi monocytes/macrophages could be overcome by blocking the CD244-CD48 interaction using anti-CD48 mAb." (PMID 30546369, 2018). "2B4 regulates the activity of NK cells or cytotoxic T cells by binding to CD48 on tumor cells or antigen-presenting cells (APCs)." (PMID 39886466, 2025). "Pan-cancer analyses reveal elevated CD48 expression across multiple tumor types relative to normal tissue." (PMID 40597436, 2025). "This approach aims to enhance CAR T-cell dwell time on tumor cells by exploiting the high abundance of CD48, thereby improving therapeutic efficacy." (PMID 40597436, 2025). "Their corresponding ligands, Ulbp1 and CD48, were highly expressed on the tumor cell surface, providing crucial activation signals for CD8+ T cell recognition of MHC class I-low or -negative tumors." (PMID 40534857, 2025). "IDO1 is positively correlated with CD274, TNFRSF9, TNFRSF4, PDCD1LG2, IDO2, and CD48 in many tumor types." (PMID 38539263, 2024). "The main goal of this study is to create an immunotherapeutic cell line, targeting CD48-expressing tumor cells." (PMID 37609636, 2023). "This is indicating an influence of the accumulation of the CD48-positive tumor cells in the tumors on the cytotoxic effects mediated by IFNγ stressing the importance of the in vivo study to evaluate the efficiency of the treatment." (PMID 37609636, 2023). "The results indicated that HO-1 suppresses CD48 expression, therefore, suppressing NK cell anti-tumor activity." (PMID 36915102, 2023). "GPI-anchored proteins on tumor cells can bind to CD48 on T cells, which in turn leads to T-cell co-stimulation and activation." (PMID 37926766, 2023). "They found that HO-1 induced Silent information regulator 1 (Sirt1) expression, an HDAC, which in turn downregulated CD48 expression, therefore inhibiting NK-cell anti-tumor functions." (PMID 36915102, 2023). "CD244 (2B4) binding to the ligand CD48 has been found to be a signaling pathway for co-stimulation or negative regulation of multiple immune cells in tumor, that currently considered to be an important marker of immune cell senescence." (PMID 38035110, 2023). "The idea behind this project is to use irradiated seYTS cells for the killing and IFNγ secretion following incubation with CD48-positive tumor cells." (PMID 37609636, 2023). "We found that 47 genes were upregulated in tumor tissues compared to normal tissues, such as CD48, TIGIT, GNLY, CCL19, CCL5, CXCL13, CCL17 and NKG7." (PMID 36713530, 2022). "CD2 and CD244 are members of the CD2 family of proteins and interact with the partner proteins CD58 and CD48 either on other T cells (homotypic) or tumor cells (heterotypic)." (PMID 35881486, 2022). "CD48 plays a vital role as an environmental sensor for regulating stem cells and inhibiting tumor development." (PMID 32426282, 2020). "We conclude that CD48 and Ly9 significantly contribute to NK cell activation in response to a classical “missing-self” tumor target cell." (PMID 27054584, 2016).